FOXO1 (forkhead box O1)
Diseases named in the same sentence as FOXO1 in open-access papers (continued):
Sharing a sentence is not in itself a finding about the gene and the disease.
malignant mesothelioma (1 paper, 2018). A malignant neoplasm of the pleura or peritoneum, arising from mesothelial cells. "Targeting the miR-182/183—FOXO1 axis could serve as a novel treatment against malignant mesothelioma." (PMID 30406026, 2018). "Therefore, miR-182 and miR-183 and FOXO1 can serve as potential therapeutic targets for treatment of malignant mesothelioma." (PMID 30406026, 2018).
MELAS (1 paper, 2017). "Apart from many targets including PINK1, FOXO1, PPARγ and Apaf-1 investigated before, MKNK2, GREM1 and EEF1A1 that might be potential targets of miR-27b-3p were revealed in the regulatory network of MELAS pathogenesis." (PMID 28139706, 2017).
mood disorder (1 paper, 2020). A cognitive disorder a disturbance in which the person's mood is hypothesized to be the main underlying feature. "In our human cohort, we observed an increase of FOXO1 expression in the NAc of depressed patients, reinforcing possible involvement of this transcription factor in mood disorders." (PMID 31974313, 2020).
muscle disorders (1 paper, 2015). "Taken together, SIRT1-mediated deacetylation of Foxo1 may represent an important therapeutic mechanism of resveratrol in muscle disorders; although whether these findings would be extrapolated in compression-induced injury in the skeletal muscle warrant further research." (PMID 26557094, 2015).
myasthenia (1 paper, 2024). "In this context, a study involving transgenic mice showed that FOXO1 overexpression in skeletal muscles caused severe myasthenia, with the in vitro and in vivo overexpression of FOXO3 increasing the activity of the Atrogin-1 promoter to further accelerate myasthenia." (PMID 38396627, 2024).
neuropathic pain (1 paper, 2022). Chronic pain caused by damage to nerve fibers. "This study explored the role of FoxO1 in chronic constriction injury (CCI)-induced neuropathic pain (NP)." (PMID 35324416, 2022).
orofacial cleft (1 paper, 2022). A disorder of facial skeleton that is characterized by cleft lip and/or cleft palate that result in feeding, speech and hearing problems caused by failures during development. "Even though the dysregulated function of FGFR1, FGFR2 and FOXO1 has been examined in non-syndromic orofacial clefts, there has been limited research regarding the comparison of these factors in one individual’s two separate locations—cleft-affected lip tissue and cleft-affected palatine tissue." (PMID 35455561, 2022). "Whilst FOXO1 polymorphism has been examined in other diseases, for instance, type 2 diabetes, no studies were found concerning orofacial clefts." (PMID 35455561, 2022). "Additionally, combining different methods to evaluate FGFR2 isoforms and FGFs could greatly impact the understanding of the roles of FGFR1, FGFR2 and FOXO1 in orofacial cleft development." (PMID 35455561, 2022). "Numerous intercorrelations between FGFR1, FGFR2 and FOXO1 do not exclude their role in the possible complex morphopathogenesis in each individual affected by orofacial clefts." (PMID 35455561, 2022).
osteitis (1 paper, 2025). "Moreover, the interaction among the transcription factor forkhead box O1 (FoxO1), Propionibacterium acnes, NLR family pyrin domain-containing protein 3 (NLRP3) inflammasomes, and IL-1β may contribute to the pathogenesis of osteitis." (PMID 41303152, 2025).
ovarian granulosa cell tumor (1 paper, 2015). A granulosa-stromal cell tumor that arises from the ovary. "FOXO1/3 and PTEN depletion in granulosa cells also promoted ovarian granulosa cell tumor development." (PMID 26287185, 2015).
Pancreatic cysts (1 paper, 2012). A cyst of the pancreas that possess a lining of mucous epithelium. "There is no report indicating the relevance between FoxO1 and human pancreatic cystic disease, and also no mechanistic implications for FoxO1 regulating pancreatic cyst formation." (PMID 22384192, 2012).
parasite (1 paper, 2025). "Furthermore, modulation of FOXO3a and FOXO1 phosphorylation required live parasite infection as no changes were observed following treatment with HK parasites or STAgs." (PMID 41450565, 2025).
parasitic infections (1 paper, 2025). "A similar situation was found in vitro for foxo1a (Forkhead box O1), a TF-coding gene that participates in mucosal (innate) immune response, regulating the expression of antimicrobial peptides and promoting phagocytosis during bacterial and parasitic infections." (PMID 40665467, 2025).
pemphigus (1 paper, 2021). Pemphigus is a group of rare autoimmune diseases that cause blistering of the skin and mucous membranes (mouth, nose, throat, eyes, and genitals).This conditioncan occur at any age, but often strikes people in middle or older age. "FOXO1, a known immunoregulatory gene, was decreased in our canine cases compared to healthy controls, which may indicate reduced ability of Tregs to function to suppress autoreactive T cells in pemphigus lesions." (PMID 34660634, 2021).
peripheral artery disease (1 paper, 2019). "Finally, we reported an upregulation of FoxO1 in ischemic skeletal muscle during peripheral artery disease that correlated with a restrained binding between MDM2 and FoxO1." (PMID 31921839, 2019).
peritonitis (1 paper, 2025). Inflammation of the peritoneum (tissue that lines the abdominal wall and covers most of the organs in the abdomen). "Conversely, Forkhead Box Protein O1 (FOXO1), Lipoprotein Lipase (LPL), and Tyrosine-protein Kinase Yes (YES1) were downregulated in peritonitis-afflicted animals when compared to the sham group." (PMID 40102905, 2025).
primary lymphedema (1 paper, 2022). A congenital condition that results in swelling in the arms or legs, and can occur during adolescence or adulthood. "The patients of primary lymphedema are susceptible to developing other comorbidities in addition to poor quality of life, such as metabolic disorders and infections, which could be caused due to dysregulated Foxo1 signaling." (PMID 36742198, 2022).
prostate tumor (1 paper, 2016). "The PD activity of AZD5363 was determined by its ability to inhibit the phosphorylation AKT substrates (FOXO1, GSK3β) and downstream pathway biomarkers (4E-BP1 and S6), after a single oral dose in prostate tumor tissue." (PMID 26910118, 2016).
pulmonary embolism (1 paper, 2017). The obstruction of the pulmonary artery or one of its branches by an embolus, sometimes associated with infarction of the lung. "In the present study, we found that pulmonary embolism decreased the mRNA and protein expression of FoxO1 compared to the sham group, possibly through a mechanism whereby downregulation of FoxO1 promotes proliferation of endothelial cells leading to vascular remodeling." (PMID 28536427, 2017).
retinal degeneration (1 paper, 2021). Degeneration of the retina. "Here, we used blue LED to induce the retinal degeneration model in rats and detected the expression of miR-27a and FOXO1 in that model." (PMID 34761005, 2021). "Thus, we hypothesized that the miR-27a-FOXO1 axis might participate in the onset of retinal degeneration." (PMID 34761005, 2021). "In this work, we aimed at unveiling the role of miR-27a-FOXO1 axis in RPE cells under oxidative stress and in blue light-emitting diode- (LED-) induced retinal degeneration (RD) rat model." (PMID 34761005, 2021).
Right ventricular hypertrophy (1 paper, 2023). In this case the right ventricle is more muscular than normal, causing a characteristic boot-shaped (coeur-en-sabot) appearance as seen on anterior- posterior chest x-rays. "FoxO1 expression is downregulated in the pulmonary vasculature and PASMCs of patients with PAH, and reconstitution of FoxO1 activity reverses vascular remodeling and right ventricular hypertrophy in vitro." (PMID 38126077, 2023).
Rotavirus infection (1 paper, 2024). Infection with any of the rotaviruses. "Probiotics and/or prebiotics might improve intestinal cell apoptosis induced by rotavirus infection through elevating antioxidant capacity and regulating some related signaling pathways (including MAPK/ERK/JNK, SIRT1/FoxO1/Rab7)." (PMID 38698473, 2024). "And probiotics and/or prebiotics might decrease cell apoptosis, and increase cell migration during rotavirus infection, which was due that probiotics and/or prebiotics elevated antioxidant capacity, and regulated some related signaling pathways (including MAPK/ERK/JNK, SIRT1/FoxO1/Rab7)." (PMID 38698473, 2024).
salivary gland tumors (1 paper, 2024). "However, there are limited reports on FoxO1 expression in salivary gland tumors." (PMID 38212454, 2024).
seminoma (1 paper, 2024). A radiosensitive malignant germ cell tumor found in the testis (especially undescended), and extragonadal sites (anterior mediastinum and pineal gland). "Focal deletions spanning cyclin A1 (CCNA1) and the transcription factor FOXO1 (13q13.3), critical for successful spermatogenesis, were found to occur exclusively in seminomas." (PMID 39461959, 2024).
Sjögren’s syndrome (1 paper, 2024). "Downregulation of FoxO1 in the salivary gland in Sjögren’s syndrome causes a direct reduction of AQP5-expressing cells." (PMID 38212454, 2024). "Downregulation of FoxO1 in the salivary glands were reported in Sjögren’s syndrome, which is characterized by a severe hypofunction of salivary glands suggests its involvement in the autoimmune response and exocrine cell death." (PMID 38212454, 2024). "Inactivation of FoxO1 induces salivary gland hypofunction in Sjögren’s syndrome." (PMID 38212454, 2024). "Tissue damage caused by FoxO1 inactivation in the salivary glands of patients with Sjögren’s syndrome also suggests that FoxO1 may regulate autoimmune responses, epigenetic modifications, cell death, and inflammation." (PMID 38212454, 2024). "PhosphoFoxO1‐S319 was detected in the minor salivary gland epithelia of patients with Sjögren’s syndrome, which is a severe hypofunction of the salivary glands, suggesting that inactivation of FoxO1 induces tissue degradation, especially in secretory units such as acini and ME cells." (PMID 38212454, 2024).
skin papilloma (1 paper, 2019). A benign papillary neoplastic growth on the skin composed of epithelial cells and a fibrous stalk. "Our findings showed that haploinsufficiency of Foxo1 accelerated the occurrence of skin papilloma, particularly in CR conditions (WT-CR vs. Foxo1+/− CR, p = 0.0103 by log-rank test), confirming the role for FoxO1 in the tumor-inhibiting effect of CR, as in Nrf2." (PMID 31888201, 2019).
status epilepticus (1 paper, 2019). Status epilepticus is defined as a continuous seizure lasting more than 30 min, or two or more seizures without full recovery of consciousness between any of them. "Oxidative stress is known to be involved in status epilepticus; in a kainic-acid-induced model of status epilepticus, salidroside showed a neuroprotective effect by regulating AMPK/SIRT1/FOXO1 signaling." (PMID 30705774, 2019).
sympathetic ophthalmia (1 paper, 2015). Sympathetic ophthalmia (SO) is a bilateral granulomatous anterior uveitis usually occurring within the three months following trauma or a surgical procedure involving one eye. "In murine EAU or human sympathetic ophthalmia eyes, miR-182 and miR-183 were downregulated following disease induction and were speculated to be associated with retinal tissue injury and Forkhead box O1 or Fas/Fas ligand system activation." (PMID 26713004, 2015).
testicular degeneration (1 paper, 2022). "In addition, we provide a new therapeutic approach using ACA and B. cereus protease to prevent DOX-induced testicular degeneration by modulating miR-155/SIRT1/FOXO1 network." (PMID 35715546, 2022).
thymic tumors (1 paper, 2019). "Previous reports also demonstrated that the loss-of-function of FOXO1 could lead to the prostate, breast, and thymic tumors formation." (PMID 30769922, 2019).
ulcerative colitis (1 paper, 2025). An inflammatory bowel disease involving the mucosal surface of the large intestine and rectum. "Mechanistic studies revealed that miR-425 directly targets the 3′UTR of forkhead box O1 (Foxo1)—a transcription factor that negatively regulates ulcerative colitis progression—leading to its suppression and consequently promoting Th17 differentiation and exacerbating intestinal inflammation." (PMID 41488657, 2025).
uremia (1 paper, 2015). A clinical syndrome associated with the retention of renal waste products or uremic toxins in the blood. "This is consistent with the observation that in muscle atrophying due to uremia, there is an increase in FOXO1 mRNA." (PMID 26656911, 2015).
uterine tumor (1 paper, 2022). "The action of psammaplysene A on cell proliferation and viability has been investigated by using the BrdU incorporation and cell viability assay, respectively, which showed that it induces cell apoptosis in uterine tumor cells via FOXO1." (PMID 35264951, 2022).
varicocele (1 paper, 2025). A condition characterized by the dilated tortuous veins of the spermatic cord with a marked left-sided predominance. "The present study revealed a significant reduction in the expression of SIRT1 and FOXO1 genes in the varicocele group, demonstrating an association with the level of ROS." (PMID 40524181, 2025). "The upregulation of SIRT1 activity modulated by M.S in the experimental group implies a potential molecular interplay between M.S and SIRT1 in varicocele-triggered OS, accompanied by increased FOXO1 expression and antioxidant capabilities." (PMID 40524181, 2025). "The molecular mechanism by which antioxidants derived from M.S alleviate varicocele involves modulation of SIRT1, FOXO1, and pro-inflammatory mediators; addressing oxidative stress and inflammation—key contributors to varicocele pathogenesis." (PMID 40524181, 2025). "In essence, this study demonstrated notable alterations in SIRT1, FOXO1, NRF2, NF-κB, and TGF-β gene expression, and in OS levels in rats induced by varicocele, which aligns with the findings of previous studies." (PMID 40524181, 2025). "The enzymatic activities of SIRT1, FOXO1, and TGF-β were significantly reduced in the testes following the development of experimental varicocele." (PMID 40524181, 2025).
vascular tumor (1 paper, 2018). "Differential expression of FOXO1 was observed in different histological grades and vascular tumor cell types." (PMID 29707114, 2018).
Wilson disease (1 paper, 2023). A very rare inherited multisystemic disease presenting non-specific neurological, hepatic, psychiatric or osseo-muscular manifestations due to excessive copper deposition in the body. "In this work, we aimed to reveal the mechanisms of GDL alleviate nerve injury through PI3K/Akt/FoxO1 and Sirt1/FoxO1 signaling pathways to inhibit autophagy in the rat models of Wilson's disease." (PMID 38010098, 2023).
X-linked hypohidrotic ectodermal dysplasia (1 paper, 2024). An X-linked form of ectodermal dysplasia which results from mutations of the gene encoding ectodysplasin. "In addition, FoxO1 induced the expression of ectodysplasin A (Eda) and its receptor Eda2r, which are known to be associated with X-linked hypohidrotic ectodermal dysplasia and are involved in salivary gland development in myoepithelial cells." (PMID 38212454, 2024).
tumor (779 papers, 2001 to 2026). "Low-dose expression of Foxo1 mutants has been shown to selectively deplete tumor-associated Treg cells, activate effector CD8+ T cells, and inhibit tumor growth without inducing autoimmunity." (PMID 40041495, 2025). "As such, using in vitro and in vivo CAR-T based approaches, FGFR4 has been targeted causing specific cytotoxicity in vitro and decreased tumor burden in vivo in an intramuscular PAX3::FOXO1 xenograft model." (PMID 40599857, 2025). "Induction of G6PD expression in FOXO1-deficient cells mitigates tumor growth inhibition and alleviates ROS level elevation." (PMID 41124013, 2025). "Both mutational changes (expression of the Pax3::Foxo1 fusion protein) and cell of origin (specific myogenic lineage in which the tumour developed) were identified as important factors contributing to the DNA methylation pattern of these tumours." (PMID 39812007, 2025). "Activation of the Heterogeneous Nuclear Ribonucleoprotein D (hnRNP D)/PPARG Coactivator 1 Alpha (PGC-1α) module enhances angiogenesis and invasion, whereas FOXO1-driven acetylation following SIRT1 loss suppresses tumor growth and promotes apoptosis." (PMID 41425553, 2025). "We previously demonstrated weak Pax3::Foxo1 RNA expression in Pax7 CreER tumours with the Pax3::Foxo1 knock‐in allele compared to much higher Pax3::Foxo1 expression in tumours forming after Pax3::Foxo1 was knocked into the other lineages." (PMID 39812007, 2025). "The context‐dependent activity of FoxO1 is likely linked to its various ‘oncogenic’ and ‘tumor‐suppressive’ functions in B cell neoplasms." (PMID 39533662, 2025). "Molecular investigations revealed that lipotoxicity induced DNA damage and mutations in metabolic regulatory genes (e.g., FOXO1, a tumor suppressor), thereby compromising cellular repair capacity." (PMID 40904774, 2025). "Using RMS tumours arising in these GEMMs, our study demonstrates a strong association between Pax3::Foxo1 expression and DNA methylation pattern." (PMID 39812007, 2025). "Based on their genotypes, we identified n = 23 tumours corresponding to the ML cluster (Pax3::Foxo1 in Myf5, Myf6, or Pax3 lineage) and n = 33 tumours corresponding to the MR cluster (other mutations in any lineage or Pax3::Foxo1 in Pax7 lineage)." (PMID 39812007, 2025). "The correlation of PAX3::FOXO1 with inferior OS decreased; however, when associated with other adverse prognostic factors such as large tumor size and older age." (PMID 39781573, 2025). "As a cancer suppressor, the loss of FOXO1 activity in tumor-infiltrating regulatory T cells leads to their accumulation in tumor tissues, triggering a strong anti-cancer immune response." (PMID 39021599, 2024). "FOXO1 overexpression enhanced CAR T cell efficacy as indicated by a significant decrease in tumour mass, which was associated with a significant increase in the number of CD8+ and CD4+ CAR T cells in the blood and spleen of treated mice." (PMID 38600376, 2024). "We found that high dietary Zn increases the relative mRNA expression of FOXO1 while tumor suppression by the Zn-deficient diet results in a decrease in the level of FOXO1 mRNA expression." (PMID 39247196, 2024). "Despite FoxO1’s reported role as a tumor suppressor, recent reports linked high FoxO1 expression to poor prognosis in B cell malignancies." (PMID 39436708, 2024). "We reasoned that if FOXO1 is the major effector, ablation of Foxo1 would rescue the loss of Rictor’s tumor growth–inhibitory effects." (PMID 39325536, 2024). "Overexpression of SIRT1 and suppression of FoxO1 cause tumor growth and increase cell survival of cancer cells." (PMID 37987301, 2023).